NFIC (nuclear factor I C)
Description:
Recognizes and binds the palindromic sequence 5'-TTGGCNNNNNGCCAA-3' present in viral and cellular promoters and in the origin of replication of adenovirus type 2. These proteins are individually capable of activating transcription and replication. Promotes telomerase reverse transcriptase transcription.
Synonyms: NF1-C; CTF; NF-I/C; NFI; NF-I; CTF5
Tractability: PROTAC: ubiquitination databases record sites on it; its protein half-life has been measured.
Gene: Protein-coding gene on chromosome 19 (3,314,403 to 3,469,217, forward strand). Ensembl gene ENSG00000141905.
Subcellular location: Nucleus
Subcellular location (Human Protein Atlas): Nucleoli fibrillar center; Nucleoplasm
Pathways (Reactome):
Gene expression (Transcription): RNA Polymerase III Abortive And Retractive Initiation; RNA Polymerase III Transcription Termination
Gene Ontology:
Molecular function: DNA-binding transcription activator activity, RNA polymerase II-specific; DNA-binding transcription factor activity; protein binding; RNA polymerase II cis-regulatory region sequence-specific DNA binding; sequence-specific double-stranded DNA binding; DNA-binding transcription factor activity, RNA polymerase II-specific
Biological process: negative regulation of transcription by RNA polymerase II; positive regulation of transcription by RNA polymerase II; regulation of transcription by RNA polymerase II; transcription by RNA polymerase II; positive regulation of DNA-templated transcription; regulation of DNA-templated transcription
Cellular component: fibrillar center; nucleoplasm; chromatin; nucleus
Genetic constraint (gnomAD): Loss-of-function variants: 12 observed, 48.75 expected, observed/expected ratio (o/e) 0.25, 90% interval 0.16 to 0.4. The upper end of that interval is the gene's LOEUF score, 0.4, which puts it in group 1 of 6, group 1 being the genes least tolerant of losing a copy. Missense variants: 575 observed, 706.44 expected, observed/expected ratio (o/e) 0.81, 90% interval 0.76 to 0.87. Synonymous variants: 322 observed, 313.28 expected, observed/expected ratio (o/e) 1.03, 90% interval 0.94 to 1.13.
Homologues: Orthologues: macaque NFIC (99% identical), dog NFIC (97% identical), pig NFIC (96% identical), chimpanzee NFIC (94% identical), tropical clawed frog nfic (82% identical), mouse Nfic (81% identical), zebrafish nfic (81% identical), rat Nfic (80% identical), Drosophila melanogaster NfI (43% identical), Caenorhabditis elegans nfi-1 (35% identical). Paralogues in human: NFIA (65% identical), NFIB (59% identical), NFIX (58% identical).
Diseases named in the same sentence as NFIC in open-access papers:
NFIC is named in the same sentence as 82 diseases in open-access papers, as found by Europe PMC text mining. Sharing a sentence is not in itself a finding about the gene and the disease. The quoted sentences say what the papers report.
breast carcinoma (17 papers, 2014 to 2025). "In breast cancer, NFIC is down-regulated and high expression is associated with better prognosis." (PMID 37353485, 2023). "The NFIC protein has greater involvement with the tumor genesis of breast cancer, gastric cancer, and glioma." (PMID 35277538, 2022). "The NFIC TFs have greater involvement with the tumor genesis of breast cancer, gastric cancer, and glioma." (PMID 36016137, 2022). "In addition, NFIC is involved in the development of several malignancies including breast cancer, brain tumor, and lung squamous cell carcinoma via the cell cycle and DNA replication pathway." (PMID 33826244, 2021). "However, NFIC is a transcription factor that plays a role in cell proliferation, differentiation, and migration during organ development and has been reported as a tumor suppressor gene in breast carcinomas, osteosarcoma, and T-cell lymphomas." (PMID 39164771, 2024). "The breast cancer cell line, MCF7, treated with NFIC siRNA, enhanced EMT, motility, migration and invasion (Lee, Lee & Park, 2015)." (PMID 32219034, 2020). "Nuclear factor I-C (NFI-C) appears to be an essential factor for the maintenance of epithelial differentiation and inhibits EMT and metastasis of breast cancer cells by regulating KLF4." (PMID 33266506, 2020). "We examined nuclear factor I-C (NFI-C) expression in MCF10A human breast epithelial cells, MCF7 non-invasive breast cancer cells, and MDA-MB231 invasive breast cancer cells by real-time PCR and western blotting." (PMID 25879941, 2015). "Also, nuclear factor I-C overexpression induced the expression of Klf4 and E-cadherin and eventually suppressed EMT, cell migration, and the invasiveness of breast cancer cells." (PMID 28422735, 2017).
bladder cancer (7 papers, 2020 to 2025). "Similarly, NFIC has been implicated in the treatment of bladder cancer and glioblastomas." (PMID 34666602, 2021). "Both ECRG4 and OGN function as tumor suppressors in the bladder, with ECRG4 overexpression inhibiting NF-kB signaling and promoting NFIC/OGN signaling in bladder cancer cells." (PMID 40051609, 2025). "It has been observed in bladder cancer that ECRG4 promotes OGN expression by upregulating NFIC, preventing the activation of NF-KB downstream pathways, thus inhibiting cell proliferation and migration." (PMID 35197484, 2022). "For instance, NFIC can promote osteoglycin expression by binding to its promoter region to repress bladder cancer by limiting cell proliferation and invasiveness." (PMID 34930914, 2021). "High expression of NFIA, NFIC and NFIX predicted worse survival outcome in patients with bladder cancer." (PMID 32219034, 2020).
gastric cancer (5 papers, 2020 to 2022). A primary or metastatic malignant neoplasm involving the stomach. "NFIC has been shown to be upregulated in several solid tumors including gastric cancer, lung squamous cell carcinoma, and colorectal cancer and is correlated with increased expression of oncogenes." (PMID 31611628, 2020). "However, the NFIC mRNA level was downregulated in gastric cancer compared with normal tissues." (PMID 32219034, 2020). "Low expression of NFIC and NFIX predicted poor OS in gastric cancer patients." (PMID 32219034, 2020).
glioma (5 papers, 2011 to 2025). A benign or malignant brain and spinal cord tumor that arises from glial cells (astrocytes, oligodendrocytes, ependymal cells). "To identify which transcription factor is a potent regulator for CYP17A1 transcription in glioma, we analyzed the correlation of CYP17A1 with NFIC, Sp1, Sp3 or GATA6 in complementary DNA microarray database of glioma." (PMID 28530704, 2017). "Additionally, the “ErbB Signaling Pathway,” “Tight Junction,” “Glioma,” and “Small Cell Lung Cancer” pathways are also prominently represented, further highlighting the broad regulatory impact of NFIA, NFIB, NFIC, and NFIX on several types of cancer." (PMID 39617063, 2025). "In a glioma cell line, NFIA and NFIC siRNAs inhibited and enhanced FABP7 promoter activity, respectively, thus indicating that FABP7 promoter activity in RCC cell lines may be weaker than that in the HEK293 cell line." (PMID 21771320, 2011). "This discrepancy might be attributed to a difference in FABP7 promoter regulation of NFIA and NFIC in RCC cell lines and glioma cell lines." (PMID 21771320, 2011).
lung carcinoma (5 papers, 2014 to 2025). "Although it remains unclear if STC‐1 is involved in the progression of lung cancer through NFIC, it is apparently worthy of further investigation in future studies." (PMID 33826244, 2021). "TLX1::NFIC, MAX and Myc are predicted to have stronger binding affinity in those individuals with the risk allele, highlighting the potential functional role of this SNP in lung cancer." (PMID 24920305, 2014).
glioblastoma (4 papers, 2021 to 2025). The most malignant astrocytic tumor (WHO grade IV). "By conducting CRISPR-Cas9–mediated genome editing of SE regions, we revealed that certain H4K5acK8ac-preferred SEs were responsible for the expression of associated genes (i.e., MYCN and NFIC) in GSCs and the maintenance of glioblastoma stem-like properties." (PMID 37759202, 2023). "To investigate whether MYCN or NFIC are involved in the maintenance of glioblastoma stem-like properties as predicted, we assessed the effects of their siRNA knockdown on 0316-GSC cells." (PMID 37759202, 2023).
leukaemia (4 papers, 2015 to 2025). "A couple of studies refer to the role of NFIC in causing neural tube defects, in monocyte differentiation and leukemia cell survival, and in osteogenesis and bone homeostasis." (PMID 41403950, 2025). "We observed a reduction in growth and colony formation of these LSCs as well as induced differentiation and apoptosis suggesting that NFIC could be an important transcription factor in MLL::AF9-associated leukemia." (PMID 36572750, 2023). "To further evaluate the role of NFIC in AML and leukemogenesis we used MLL::AF9 transformed model of leukemia." (PMID 36572750, 2023).
lung squamous cell carcinoma (4 papers, 2020 to 2023). "One study reported that NFIC was a low expression in human Lung Squamous Cell Carcinoma (LUSC) tissues and cell lines, and it inhibited the proliferation of LUSC cells and promoted apoptosis in vitro and in vivo." (PMID 37457582, 2023).
pancreatic cancer (4 papers, 2019 to 2024). "Previously, a study revealed that cigarette smoke condensate promoted METTL3 overexpression by inducing hypomethylation of METTL3 promoter and recruitment of the transcription factor NFIC in pancreatic cancer." (PMID 38481809, 2024). "Previous studies have shown that cigarette smoke condensate induces hypomethylation of the METTL3 promoter and, subsequently, recruitment of the transcription factor NFIC to induce METTL3 overexpression in pancreatic cancer." (PMID 36550779, 2023). "Similar to the effect of METTL3 depression, NFIC knockdown also substantially inhibited CSC-induced miR-25-3p overexpression in HPDE6-C7 and pancreatic cancer cells." (PMID 31015415, 2019).
diabetic nephropathy (3 papers, 2021 to 2023). "Currently, several studies have indicated that nuclear factor I/C (NFIC) is the nuclear factor I family that might be implicated in the regulation of diabetic-related diseases, such as diabetic retinopathy and diabetic nephropathy." (PMID 37710299, 2023). "Furthermore, it has been reported that overexpressing NFIC might relieve HG-triggered inflammation and fibrosis in mouse podocytes in diabetic nephropathy." (PMID 37710299, 2023). "Furthermore, NFIC is related to digestive system carcinoma and regulates renal inflammation and renal fibrosis in patients with diabetic nephropathy." (PMID 35923698, 2022).
endometrial cancer (3 papers, 2016 to 2025). Primary or metastatic malignant neoplasm involving the endometrium (mucous membrane that lines the endometrial cavity). "NFIC is a lesser-known transcription factor that has been shown to be a favorable prognostic marker in endometrial cancer." (PMID 33450975, 2021).
melanoma (3 papers, 2015 to 2020). A malignant, usually aggressive tumor composed of atypical, neoplastic melanocytes. "Compared with normal tissues, NFIC mRNA expression level was reduced in tumors in 18 studies involving 10 types of cancers, however, an increased level was observed in lymphomas and melanomas in only six studies." (PMID 32219034, 2020). "A2058 human melanoma cells engineered to over-express either BRN2 or MITF were analyzed by qRT-PCR for expression of all four members of the NFI gene family, NFIA, NFIB, NFIC and NFIX." (PMID 28119061, 2017).
osteoporosis (3 papers, 2017 to 2022). A condition of reduced bone mass, with decreased cortical thickness and a decrease in the number and size of the trabeculae of cancellous bone (but normal chemical composition), resulting in increased fracture incidence. "Studies have shown that NFIC is closely linked to osteogenic differentiation, and found that the expression of NFIC in osteoblasts of patients with human osteoporosis was decreased, but this is still in the stage of basic research and there is little research on poultry." (PMID 32970714, 2020). "Further work will focus on the exact contribution of NFIC, BACH1, CEBPB, and POU2F2 to osteoporosis pathogenesis." (PMID 35757392, 2022). "The core transcription factors in the ceRNA network, NFIC, BACH1, CEBPB, and POU2F2, might be related to osteoporosis." (PMID 35757392, 2022).
osteosarcoma (3 papers, 2018 to 2024). A usually aggressive malignant bone-forming mesenchymal neoplasm, predominantly affecting adolescents and young adults. "Four other TF were also found with a high number of connections and appear to be associated with osteosarcoma (EWSR1-FLI1 and NFIC), cranium formation (TCF3), soft tissue calcification and chondrocyte differentiation (NF-KAPPAB)." (PMID 32493207, 2020). "Only NFIC, a validated target of miR-210 from miRBase and a DEG from a gene expression profile GSE38135, had been shown to play important role in TGF-b1-induced osteosarcoma dedifferentiation and can be significantly reduced by miR-210 treatment in human osteosarcoma cell line MNNG/HOS." (PMID 29760609, 2018).
prostate carcinoma (3 papers, 2019 to 2022). A carcinoma that arises from epithelial cells of the prostate gland. "This close correlation of TBX3 and NFIC dependency with that observed for FOXA1 supports the conclusion that TBX3 and NFIC regulate prostate cancer cell viability in the AR setting." (PMID 35550030, 2022). "We found that TBX3 and NFIC genomic amplifications together represented up to 13.3% of prostate cancers, in which notably higher amplification rates were observed in mCRPC studies as opposed to those sampling primary prostate cancer." (PMID 35550030, 2022). "TBX3 and NFIC, two nuclear factors that are amplified or overexpressed in mCRPC, were vulnerabilities in other prostate cancer models, including ones that were ART resistant, and bound to FOXA1 transcription regulatory elements." (PMID 35550030, 2022). "To examine the relative contribution of TBX3 and NFIC to cell viability, we analyzed genome-scale RNAi screens performed in eight prostate cancer cell lines as a part of Project Achilles 2.20.1." (PMID 35550030, 2022). "In the TCGA database, NFIA, NFIB and NFIC mRNA levels were significantly downregulated in prostate cancer patients." (PMID 32219034, 2020). "NFIC mRNA levels were downregulated in prostate carcinoma according to Luo2’s dataset." (PMID 32219034, 2020). "Indeed, NFIC, a potential co-factor found in our ChIP-seq analysis in female tissues, has been found to function as a co-repressor of ARTGs in prostate cancer epithelial cells." (PMID 31350272, 2019). "In promoting proliferation in ART, CREB5 exhibited a strong degree of interaction with known AR transcription machinery, including FOXA1, HOXB13, and GRHL2, as well as novel prostate cancer regulators TBX3 and NFIC." (PMID 35550030, 2022). "Together, we found TBX3 and NFIC were nuclear proteins associated with CREB5, FOXA1, and functionally impacted prostate cancer cell viability and ART resistance even absent of CREB5." (PMID 35550030, 2022). "Furthermore, upon computing the average dependency scores in DEMETER, we found that NFIC and TBX3 ranked among the strongest dependencies in these prostate cancer cell lines while exhibiting limited overall dependency in the other 495 cell lines." (PMID 35550030, 2022). "We note that we also found peptides from LBD1 and DNMT1, but further evaluation showed that these proteins did not exhibit as strong a difference in AR-expressing prostate cancer cells, and we therefore concentrated on NFIC and TBX3, which also interacted with FOXA1 in our other RIME experiments." (PMID 35550030, 2022).
Alzheimer disease (2 papers, 2020 to 2021). A progressive, neurodegenerative disease characterized by loss of function and death of nerve cells in several areas of the brain leading to loss of cognitive function such as memory and language. "Moreover, genome-wide association studies have revealed that genetic variants of NFIC are also associated with Alzheimer’s disease." (PMID 34930914, 2021). "GWAS study revealed genetic variants of NFIC is associated with Alzheimer’s disease." (PMID 33080834, 2020).
cervical cancer (2 papers, 2020 to 2021). A primary or metastatic malignant neoplasm involving the cervix. "The Oncomine database showed significant differences in mRNA expression of NFIB and NFIC between cervical cancer and normal tissues." (PMID 32219034, 2020).
COVID-19 (2 papers, 2023). A disease caused by infection with severe acute respiratory syndrome coronavirus 2. "At endpoint A, the gene encoding NFIC is upregulated in the SEV group compared to controls (contrast 2), suggesting an important role for this TF in the transcription of inflammatory genes in severe COVID-19." (PMID 36993968, 2023).
esophageal cancer (2 papers, 2020). A primary or metastatic malignant neoplasm involving the esophagus. "Esophageal cancer-related gene-4 inhibits the NF-κB signaling pathway by promoting NFIC/OGN signaling in BCa cells." (PMID 32922434, 2020).
Obesity (2 papers, 2021 to 2023). Accumulation of substantial excess body fat. "Our study also identified several other genes, such as ZNF827, MIR7641-2, RAPTOR, KSR1, GTF3C3, and NFIC, whose role in obesity or obesity-related disorders has been consistently shown in previous studies." (PMID 37204309, 2023). "A study suggested that NFIC could balance adipogenic and osteogenic differentiation through the Wnt signaling pathway, which was regarded as a novel target for controlling metabolic disorders, such as obesity." (PMID 34828435, 2021).
acute myeloid leukemia (1 paper, 2023). Acute myeloid leukemia (AML) is a group of neoplasms arising from precursor cells committed to the myeloid cell-line differentiation. "Here we show NFIC protein is significantly overexpressed in 69% of acute myeloid leukemia patients." (PMID 36572750, 2023).
autism spectrum disorder (1 paper, 2021). A spectrum of developmental disorders that includes autism, and Asperger syndrome. "In addition, through RNA-seq gene expression profiling of the brain, NFIC has been shown to regulate differentially expressed genes in autism spectrum disorder." (PMID 34930914, 2021).
cervical squamous cell carcinoma (1 paper, 2020). A squamous cell carcinoma arising from the cervical epithelium. "In Biewenga’s study, the NFIC mRNA expression was also reduced in cervical squamous cell carcinoma compared with normal tissues." (PMID 32219034, 2020). "The results showed lower mRNA expression of NFIB, NFIC and NFIX predicted worse OS in cervical squamous cell carcinoma." (PMID 32219034, 2020).
chronic pancreatitis (1 paper, 2023). A chronic inflammatory process causing damage and fibrosis of the pancreatic parenchyma. "Mutations leading to protein misfolding, activation of the UPR, and ER stress cause chronic pancreatitis and can contribute to the risk of PDAC52, further supporting the role of NFIC in pancreatic homeostasis and disease." (PMID 37353485, 2023).
ductal breast carcinoma (1 paper, 2020). "NFIC mRNA level was decreased in ductal breast carcinoma and lobular breast carcinoma in studies in which Richardson2 and Sorlie2 databases were utilized." (PMID 32219034, 2020).
endometriosis (1 paper, 2025). The growth of functional endometrial tissue in anatomic sites outside the uterine body. "The results indicated that 13 TFs were identified in both SLE and endometriosis, and 6 of them (EP300, TCF12, CTCF, POLR2A, CEBPB and NFIC) can act on four potential co-diagnostic genes simultaneously." (PMID 39744159, 2025).
esophageal adenocarcinoma (1 paper, 2020). A malignant tumor with glandular differentiation arising predominantly from Barrett mucosa in the lower third of the esophagus. "Low expression of NFIC and NFIX revealed poor prognosis in esophageal adenocarcinoma patients." (PMID 32219034, 2020).